RNF220 (ring finger protein 220)
Description:
E3 ubiquitin-protein ligase that promotes the ubiquitination and proteasomal degradation of multiple substrates including GRIA1, GRIA2, PHOX2A and PHOX2B, STAT1, STAT3 and SIN3B. Independently of its E3 ligase activity, acts as a CTNNB1 stabilizer through USP7-mediated deubiquitination of CTNNB1 promoting Wnt signaling. Plays a critical role in the regulation of nuclear lamina. Modulates synaptic activity and brain functions by promoting degradation of AMPA receptor subunits GRIA1 and GRIA2. The RNF220/ZC4H2 complex monoubiquitinates PHOX2A and PHOX2B to enhance their DNA-binding ability and transactivity (By similarity). Promotes 'Lys-63'-linked polyubiquitination of Gli transcriptional activators and repressors, facilitating their nuclear export by CRM1 to fine-tune the sonic hedgehog/Gli signaling (By similarity). Regulates type I and type II interferon responses upon viral or bacterial infection by mediating 'Lys-63'-linked polyubiquitination of STAT1. Also regulates STAT3 phosphorylation, nuclear translocation, and transcriptional activity via ubiquitination. Promotes OLIG1 and OLIG2 'Lys-63'-linked polyubiquitination and stabilization, two master regulatory transcription factors involved in oligodendroglial development.
Synonyms: C1orf164; FLJ10597; HLD23
Tractability: PROTAC: UniProt records ubiquitination sites on it; ubiquitination databases record sites on it; its protein half-life has been measured.
Gene: Protein-coding gene on chromosome 1 (44,405,185 to 44,651,724, forward strand). Ensembl gene ENSG00000187147.
Subcellular location: Cytoplasm; Nucleus
Subcellular location (Human Protein Atlas): Nucleoplasm
Pathways (Reactome):
Immune System: Antigen processing: Ubiquitination & Proteasome degradation
Gene Ontology:
Molecular function: beta-catenin binding; protein binding; ubiquitin protein ligase activity; ubiquitin-protein transferase activity; metal ion binding
Biological process: positive regulation of canonical Wnt signaling pathway; positive regulation of transcription by RNA polymerase II; protein monoubiquitination; protein polyubiquitination; regulation of transcription regulatory region DNA binding; positive regulation of myelination; positive regulation of type I interferon-mediated signaling pathway; protein autoubiquitination; protein ubiquitination; positive regulation of signal transduction
Cellular component: cytoplasm; nuclear lamina; nucleoplasm; nucleus; protein-containing complex
Genetic constraint (gnomAD): Loss-of-function variants: 6 observed, 68.24 expected, observed/expected ratio (o/e) 0.0879, 90% interval 0.047 to 0.17. The upper end of that interval is the gene's LOEUF score, 0.17, which puts it in group 1 of 6, group 1 being the genes least tolerant of losing a copy. Missense variants: 563 observed, 778.92 expected, observed/expected ratio (o/e) 0.72, 90% interval 0.67 to 0.77. Synonymous variants: 270 observed, 299.02 expected, observed/expected ratio (o/e) 0.9, 90% interval 0.82 to 1.
Homologues: Orthologues: chimpanzee RNF220 (100% identical), macaque RNF220 (99% identical), guinea pig RNF220 (99% identical), pig RNF220 (99% identical), rabbit RNF220 (99% identical), rat Rnf220 (98% identical), mouse Rnf220 (98% identical), tropical clawed frog rnf220 (89% identical), dog RNF220 (43% identical), zebrafish rnf220a (40% identical), zebrafish rnf220b (37% identical), Drosophila melanogaster RNF220 (22% identical).
Diseases named in the same sentence as RNF220 in open-access papers:
RNF220 is named in the same sentence as 33 diseases in open-access papers, as found by Europe PMC text mining. Sharing a sentence is not in itself a finding about the gene and the disease. The quoted sentences say what the papers report.
medulloblastoma (5 papers, 2020 to 2023). A malignant, invasive embryonal neoplasm arising from the cerebellum. "RNF220 is associated with progression of leukemia or medulloblastoma." (PMID 36199791, 2022). "RNF220 mediates medulloblastoma development by epigenetic modulation of Shh signal pathway, as well as accelerates the leukemic cells proliferation and declines the Cyclin D1 protein degradation." (PMID 34753387, 2021). "During cerebellum development and medulloblastoma progression, RNF220 promotes Shh signaling epigenetically through targeting EED for degradation, overwriting its effects on Gli ubiquitination." (PMID 32630355, 2020). "In cerebellar granule neuron progenitors and medulloblastoma cells, RNF220 targets EED for degradation and promotes Shh signaling epigenetically." (PMID 32630355, 2020). "RNF220 is a member of RING finger domain ubiquitin E3 ligases, and RNF220 knockdown inhibited medulloblastoma progression." (PMID 34753387, 2021).
leukemia (3 papers, 2022 to 2025). A malignant (clonal) hematologic disorder, involving hematopoietic stem cells and characterized by the presence of primitive or atypical myeloid or lymphoid cells in the bone marrow and the blood. "In leukemia, it was reported that RNF220 promotes the proliferation of leukemic cells and reduces the degradation of the CyclinD1 protein through USP22, which indicated that RNF220 might play an important role in the progression of AML." (PMID 41244923, 2025). "RNF220 stimulates the growth of leukemia cells by diminishing the breakdown of Cyclin D1 protein." (PMID 39048945, 2024).
colon cancer (2 papers, 2021 to 2022). "RNF220 is involved in the activation of Wnt pathway in colon cancer cells and promotes the deubiquitination of β-catenin." (PMID 34753387, 2021). "In this study, we found that RNF220 promoted the stemness and progression of colon cancer cells via the USP22-BMI1 axis." (PMID 34753387, 2021). "In conclusion, RNF220 promoted the stemness and progression of colon cancer cells via the USP22-BMI1 axis." (PMID 34753387, 2021). "Previous study found that microRNA-301b-3p facilitated cell proliferation and migration in colorectal cancer by targeting HOXB1, while in our study, we identified a novel molecule named RNF220, which was aberrantly expressed in colon cancer." (PMID 34753387, 2021). "The RNF220 gene encodes a RING domain E3 ubiquitin ligase which is a regulator of β-catenin and promotes canonical Wnt signaling, has been reported to meditate tumorigenesis in colon cancer." (PMID 35273637, 2022). "In this study, we hypothesized RNF220 promoted the stemness and progression of colon cancer cells via the USP22-BMI1 axis, with the aim to investigate specific role and related mechanism of RNF220 in colon cancer." (PMID 34753387, 2021). "TCGA shows high expression of RNF220 in colon cancer, but the specific role and related mechanism of RNF220 in colon cancer pathogenesis remain unclear." (PMID 34753387, 2021). "In this study, we hypothesized RNF220 promoted the stemness and progression of colon cancer cells via the USP22-BMI1 axis, with the aim to investigate the specific role and related mechanism of RNF220 in colon cancer." (PMID 34753387, 2021). "Taken together, we discovered that RNF220 functioned as an oncogenic factor by promoting the stemness the progression of colon cancer via the USP22-BMI1 axis, shedding lights on RNF220 as a potential therapeutic targets for colon cancer treatment from bench to clinic." (PMID 34753387, 2021).
Intellectual disability (2 papers, 2024 to 2025). "Neurobehavioral analyses indicate altered learning and memory capabilities in RNF220-deficient mice, with mutations in the RNF220 gene contributing to neurodevelopmental disorders such as intellectual disability." (PMID 40761314, 2025). "It is known that myelin dysfunction has a profound effect on neurological functions including processing information during high cognition, and patients with RNF220 mutations have symptoms of intellectual disability." (PMID 38324685, 2024). "Individuals harboring homozygous R363Q or R365Q mutation of RNF220 have symptoms of leukodystrophy and corpus callosum agenesis, as well as intellectual disability." (PMID 38324685, 2024).
acute lymphoblastic leukemia (1 paper, 2025). Leukemia with an acute onset, characterized by the presence of lymphoblasts in the bone marrow and the peripheral blood. "Analysis of pan-cancer RNA sequencing data from The Cancer Genome Atlas (TCGA) showed that RNF220 was upregulated in most tumor tissues, with particularly significant upregulation observed in both AML and acute lymphoblastic leukemia (ALL)." (PMID 41244923, 2025).
breast carcinoma (1 paper, 2025). "Regarding RNF220 upregulation, multi-database analysis identified FOXA1 as a negative transcriptional regulator—this epigenetic modulator directly binds androgen receptor promoters, serves as an ER+ breast cancer biomarker, and drives progression in prostate/breast cancers via mutational activation." (PMID 41244923, 2025).
colorectal cancer (1 paper, 2021). A primary or metastatic malignant neoplasm that affects the colon or rectum. "We validated the role of RNF220 in vivo and in vitro, demonstrating RNF220 promoted colorectal cancer growth." (PMID 34753387, 2021). "Western blot and RT-PCR assays were applied to examine the protein levels of RNF220 in normal colonic mucosa and colorectal cancer cells." (PMID 34753387, 2021). "In this study, we discovered that RNF220 level was elevated in colorectal cancer, promoting the migration, invasion and proliferation of colorectal cancer cells through USP22-BMI1 axis." (PMID 34753387, 2021). "Together, these results demonstrated that RNF220 promoted the proliferation, invasion and migration in colorectal cancer cell models." (PMID 34753387, 2021). "RNF220 knockdown notably suppressed the sphere-propagating capacity, while RNF220 overexpression strengthened the sphere-propagating ability in colorectal cancer cell SW480." (PMID 34753387, 2021). "Spheroid formation and western blot assays illustrated that RNF220 promoted the stemness of colorectal cancer cells." (PMID 34753387, 2021). "RNF220 promoted the proliferation and migration, invasion of colorectal cancer cells through BrdU incorporation, clone formation, transwell and wound healing assays." (PMID 34753387, 2021). "RNF220 promoted the invasion, migration and proliferation of colorectal cancer cells, by contributing to stemness of cancer cells." (PMID 34753387, 2021). "Subsequently, in vitro assays were employed to assess the functions of RNF220 in colorectal cancer." (PMID 34753387, 2021). "In this study, we observed RNF220 was highly expressed in colorectal cancer cells and tissues." (PMID 34753387, 2021). "Meanwhile, RNF220 contributed to the stemness of colorectal cancer cells." (PMID 34753387, 2021). "RNF220 promoted the proliferation, migration and invasion of colorectal cancer cells." (PMID 34753387, 2021). "Taken together, we discovered RNF220 expressed highly in colorectal cancer." (PMID 34753387, 2021). "We found that RNF220 was upregulated in colorectal cancer in patients and cell models." (PMID 34753387, 2021). "Taken together, these results revealed that RNF220 was expressed highly in colorectal cancer." (PMID 34753387, 2021). "We found that RNF220 was highly expressed in colorectal cancer tissues and cells, which facilitated the proliferation, migration and invasion of colorectal cancer cells, and thus promoting the stemness of colorectal cancer cells." (PMID 34753387, 2021). "However, the effects of RNF220 on colorectal cancer fate determination remains blearily." (PMID 34753387, 2021). "It is noteworthy that RNF220 regulates BMI1 expression via USP22, therefore, USP22-BMI1 axis was validated in this study to function in colorectal cancer progression." (PMID 34753387, 2021). "We also examined the RNF220 expression level in normal colonic mucosa NCM460 cells and colorectal cancer cells SW480, HCT116, SW620 and SW837." (PMID 34753387, 2021). "All these results illustrated the pro-tumorigenic effects of RNF220/USP22/BMI1 signal pathway on proliferation and stemness of colorectal cancer, providing novel insights into RNF220 as clinical therapeutic candidates for future drug design and development targeting colorectal cancer." (PMID 34753387, 2021).
colorectal tumor (1 paper, 2021). "Next, we discovered the mRNA and protein levels of RNF220 were upregulated in colorectal tumor compared with those in para-carcinoma tissue from 65 patients." (PMID 34753387, 2021). "According to TCGA database, RNF220 expression level was elevated in colorectal tumor (n = 286) compared with that in normal tissue (n = 41)." (PMID 34753387, 2021). "Firstly, RT-PCR assay was used to compare differences between expression levels of RNF220 in colorectal tumor and normal tissues." (PMID 34753387, 2021).
embryonal carcinoma (1 paper, 2024). A non-seminomatous malignant germ cell tumor characterized by the presence of large germ cells with abundant cytoplasm resembling epithelial cells, geographic necrosis, high mitotic activity, and pseudoglandular and pseudopapillary structures formation. "In P19 embryonal carcinoma cells, the retinoic acid-induced Hox expression was further stimulated by Rnf220 knockdown, which can also be rescued by Wdr5 knockdown." (PMID 39526890, 2024).
leukodystrophy (1 paper, 2024). Leukodystrophies are a group of rare, progressive, metabolic, genetic diseases that affect the brain, spinal cord and often the peripheral nerves. "Together, these results indicate that the oligodendroglial development and myelination are impaired by the leukodystrophy-related RNF220 missense mutation." (PMID 38324685, 2024). "Together, these results indicate that leukodystrophy-related RNF220 mutations impair its regulation of ubiquitination of Olig1 and Olig2 and their protein stability." (PMID 38324685, 2024). "In this study, we present ample evidence that dysregulation of RNF220-regulated ubiquitination and stabilization of Olig proteins are implicated in the pathology of leukodystrophy." (PMID 38324685, 2024). "Collectively, these results indicate that RNF220 deficiency in OL lineage cells leads to leukodystrophy-like malfunction of learning and memory behaviors." (PMID 38324685, 2024). "Together, all these results suggest that RNF220 mutations impair the regulation of Olig proteins stability and oligodendroglial development, which can serve as a potential etiological mechanism for leukodystrophy pathogenesis." (PMID 38324685, 2024). "Here, we find that RNF220, a known leukodystrophy-related E3 ubiquitin ligase, is required for oligodendroglial development." (PMID 38324685, 2024). "However, the physiological roles of RNF220 during oligodendroglial development and its ability to regulate TFs during leukodystrophy onset are unclear." (PMID 38324685, 2024).
mental disorder (1 paper, 2022). A disease that has its basis in the disruption of mental process. "It is also of interest to study if Rnf220 is implicated in the maintenance of 5-HTNs and oligodendrocytes in the adult brain as these two types of cells are involved in mental disorders and neurodegenerative diseases." (PMID 35399523, 2022).
rectal cancer (1 paper, 2014). A primary or metastatic malignant neoplasm that affects the rectum. "Notably, many of these genes (ADRA1A, BARHL2, ERAS, ESRRG, RNF220 and ST6GALNAC5) are also targets of the Polycomb Repressor Complex-2, further supporting an important role of epigenetic crosstalk in controlling rectal cancer therapeutic responsiveness." (PMID 25261372, 2014).
tumor (4 papers, 2017 to 2025). "In medulloblastoma, RNF220 facilitates tumor proliferation and progression by activating the Sonic Hedgehog signaling pathway." (PMID 41244923, 2025). "To validate functions of RNF220 in vivo, we established the subcutaneous xenograft tumor mice model which stably knocked down RNF220 (n = 5)." (PMID 34753387, 2021). "To investigate the relationship between RNF220 and the tumor immune microenvironment, we first employed the xCELL algorithm to analyze RNA-seq data from AML and ALL patients in the TCGA and TARGET cohorts, assessing correlations between RNF220 expression and immune cell subtype proportions." (PMID 41244923, 2025). "RNF220 promoted tumor proliferation by suppressing apoptosis and preventing G1 arrest." (PMID 41244923, 2025). "This suggests that patients with high RNF220 expression may exhibit immune evasion within the tumor microenvironment." (PMID 41244923, 2025). "Furthermore, we analyzed the correlation between RNF220 and tumor immune evasion-related genes across pan-cancer datasets." (PMID 41244923, 2025). "Furthermore, our in vivo model suggested that RNF220 promoted tumor growth by regulating the USP22-BMI1 axis." (PMID 34753387, 2021). "Finally, we discovered that RNF220 facilitated tumor growth in vivo through establishment of subcutaneous xenograft tumor mice model." (PMID 34753387, 2021). "Furthermore, 30 days-post injection, the tumor volume and weight were significantly decreased in shRNA-RNF220 group, suggesting an oncogenic role of RNF220." (PMID 34753387, 2021). "Finally, we found that RNF220 facilitated tumor development in vivo." (PMID 34753387, 2021). "To further investigate the impact of RNF220 on tumor cells, we stratified patients from the TCGA-LAML and TARGET-LAML cohorts into high- and low-expression groups based on RNF220 levels." (PMID 41244923, 2025). "Considering that tumor mutational burden (TMB) is also an integral component of the tumor immune landscape, we further assessed the correlation between TMB and RNF220 expression." (PMID 41244923, 2025). "We show that USP7-mediated β-catenin deubiquitination is a tumor-specific event when APC is truncated and that it is RNF220 independent." (PMID 29045831, 2017). "In addition, our study shows that depletion of RLIM inhibits MB cell growth in vitro and tumor formation in vivo, at least partially, by stabilizing the ZC4H2/RNF220 complex." (PMID 35040952, 2022). "RNF220 regulated BMI1 expression through USP22, promoting tumor growth in vivo." (PMID 34753387, 2021).
cancer (3 papers, 2019 to 2025). A tumor composed of atypical neoplastic, often pleomorphic cells that invade other tissues. "This study builds upon our group’s previous findings to explore RNF220 expression across pan-cancers." (PMID 41244923, 2025). "Subsequent pan-cancer prognostic analysis indicated that high RNF220 expression was an adverse prognostic factor in most malignancies." (PMID 41244923, 2025). "Recently, several studies report RNF220 regulates progression in various types of cancers." (PMID 34753387, 2021).
hematological malignancies (1 paper, 2025). "This analysis revealed strong positive correlations between RNF220 expression and key biological processes in hematological malignancies, including tumorigenesis, apoptosis, differentiation, and epithelial–mesenchymal transition (EMT)." (PMID 41244923, 2025).
infection (1 paper, 2024). The state of being infected such as from the introduction of a foreign agent such as serum, vaccine, antigenic substance or organism. "We previously showed that RNF220 is expressed in bone marrow macrophages, which is responsive to pathogenic infection and IFN signaling." (PMID 39336725, 2024).
RNF220 also shares sentences with these, for which no sentence is quoted: neurodegenerative disease (2 papers); acute myeloid leukemia (1); amyotrophic lateral sclerosis (1); Ataxia (1); atrial fibrillation (1); Brugada syndrome (1); cholangiocarcinoma (1); coronary artery disease (1); deafness (1); gastric cancer (1); hepatopathy (1); neurodevelopmental disorder (1); non-small cell lung carcinoma (1); Obesity (1); pediatric acute myeloid leukemia (1); progressive ataxia and (1); schizophrenia (1).